GAST (gastrin)
Diseases named in the same sentence as GAST in open-access papers (continued):
Sharing a sentence is not in itself a finding about the gene and the disease.
head and neck carcinoma (1 paper, 2022). A carcinoma that arises from the head and neck region. "The aim of this study was to analyze the relationship of serum gastrin-17 (G-17) and oral mucositis in head and neck carcinoma (HNC) patients receiving radiotherapy." (PMID 36269422, 2022).
Hepatitis (1 paper, 2023). Inflammation of the liver. "However, these drugs can cause side-effects that cannot be ignored, such as hepatitis, nephritis, osteoporotic fracture and gastrin." (PMID 37513438, 2023).
hyperplasia (1 paper, 2024). An abnormal increase in the number of cells in an organ or a tissue with consequent enlargement. "Gastrin is a hormone involved in regulating gastric acid production, and its elevation suggests a potential risk of gastric hyperplasia or cancer." (PMID 38672316, 2024).
hypochromic anemia (1 paper, 2020). Anemia caused by the reduction of hemoglobin in relation to the red cell volume. "Laboratory tests showed elevated gastrin serum levels and presence of antibodies antiparietal cells, as well as microcytic hypochromic anemia compatible with chronic iron deficiency." (PMID 33395833, 2020).
insomnia (1 paper, 2020). A sleep disorder characterized by difficulty in falling asleep and/or remaining asleep. "Insomnia and sleep deprivation can cause increased production of gastrin, regulating gastric acid secretion and motilin (MTL) that activate pepsin." (PMID 32617111, 2020). "The stomach is particularly sensitive to stress, and insomnia can activate the sympathetic nervous system to cause the adrenal medulla to secrete catecholamine, which has a role in regulating the secretion of gastrin (GAS) and stomach acid." (PMID 32617111, 2020).
intestinal polyp (1 paper, 2023). Discrete abnormal tissue masses that protrude into the lumen of the intestine. "Hp causes hyperplasia of the intestinal mucosa by increasing the levels of gastrin, which can lead to the development of intestinal polyps." (PMID 37337163, 2023).
liver disease (1 paper, 2025). "Changes in pepsinogen levels in liver disease are not entirely understood and likely relate to many factors, including inflammation, altered gastrin levels, and Helicobacter pylori infection." (PMID 42112040, 2025).
liver tumours (1 paper, 2013). "The majority of liver tumours express cholecystokinin (CCK-B) receptors and are able to process gastrin (G) as far as pro-G and G-gly (precursor forms) and this may be associated with tumour proliferation." (PMID 24137355, 2013). "The majority of liver tumours express cholecystokinin (CCK-B) receptors and are able to process gastrin (G) as far as pro-G and G-gly (the precursor forms), which may be associated with tumour proliferation." (PMID 24137355, 2013).
macrocytic anemia (1 paper, 2023). Anemia that is characterized by increased red blood cell volume. "Subsequent serum evaluation was consistent with pathologic diagnosis, demonstrating an elevated fasting gastrin level and an elevated parietal cell antibody level without macrocytic anemia or vitamin B12 depletion, further supporting a diagnosis of AIG." (PMID 37507704, 2023).
melanoma (1 paper, 2023). A malignant, usually aggressive tumor composed of atypical, neoplastic melanocytes. "Taken as a whole, the data raise the possibility that increased circulating gastrin concentration should be considered a modifiable risk factor for melanoma progression." (PMID 38069171, 2023). "In 89 melanoma patients, we found a statistically significant association between circulating gastrin concentrations and melanoma thickness and metastasis, which are known risk factors of melanoma progression and prognosis." (PMID 38069171, 2023). "Surprisingly, higher fasting serum gastrin concentrations were associated with advanced melanoma stages." (PMID 38069171, 2023). "There were also moderately raised fasting serum gastrin concentrations associated with H. pylori sero-positive melanoma patients (OR 5.36, p < 0.0023; Fisher exact test p < 0.002)." (PMID 38069171, 2023). "The data raise the prospect that circulating gastrin is a risk factor for melanoma progression." (PMID 38069171, 2023). "Our data suggest that in a subset of melanoma patients, an elevated serum gastrin concentration is a risk factor for melanoma tumor progression, and that gastrin may act on both melanoma and adjacent stromal cells through CCK2 receptors to promote mechanisms of tumor migration and invasion." (PMID 38069171, 2023). "The data therefore point to indirect effects of gastrin in stimulating melanoma cell invasion mediated by dermal fibroblasts." (PMID 38069171, 2023). "We then examined serum gastrin concentrations in 89 melanomas with a mean tumor thickness of 2.9 ± 0.3 mm." (PMID 38069171, 2023). "All but two of the melanoma patients with serum gastrin above the reference range were either H. pylori positive or on proton pump inhibitor (PPI) medication, or both." (PMID 38069171, 2023). "Crucially, however, these direct effects appear to be relatively weak, and in the presence of matrix and dermal fibroblasts, gastrin-stimulated melanoma cell invasion is indirect and is mediated by fibroblasts, at least some of which also express CCK2R." (PMID 38069171, 2023). "In the present study, we have explored this hypothesis through re-examination of CCK2R expression, determination of circulating amidated gastrin in melanoma patients, and exploration of the effects of gastrin on melanoma cell migration and invasion." (PMID 38069171, 2023). "Since stromal cells also express functional CCK2R, gastrin could act both directly to stimulate melanoma cells and indirectly via stromal cells." (PMID 38069171, 2023). "Interestingly, the probability of elevated gastrin was significantly greater in the sub-group of melanoma patients with stage 2 (18 out of 44) compared with stage 1 (3 out of 42) disease (OR 8.5, p < 0.0005; Fisher exact test p < 0.0003)." (PMID 38069171, 2023). "The secretomes derived from melanoma cells were subjected to proteomic analysis, leading to the identification of candidate proteins that are responsible for the rapid degradation of the extracellular matrix in response to gastrin stimulation." (PMID 38069171, 2023). "Thus, the proteomic and functional data suggest that gastrin influences melanoma progression by targeting components involved in the regulation of protease activity and inhibitor function." (PMID 38069171, 2023). "Moreover, restaging of patients following the acquisition of lymph node data from sentinel biopsy and/or lymph node dissection showed a correlation between elevated serum gastrin concentration and melanoma progression, as indicated by the presence of regional lymph node metastasis." (PMID 38069171, 2023). "Altogether, our findings suggest that gastrin may exert both direct and indirect effects on melanoma cells by enhancing their migration and invasion capabilities, possibly by altering the balance towards the dominance of secreted proteases, e.g., MMP-2, against protease inhibitors, e.g., TIMP-3." (PMID 38069171, 2023).
melanoma (continued). "However, the data suggest that in those melanoma patients with increased serum gastrin, the hormone may play a role in disease progression." (PMID 38069171, 2023). "Melanoma cell growth was recently shown to be suppressed by cholecystokinin/gastrin (CCK) receptor antagonists, and our preliminary data suggested that melanoma patients with Helicobacter gastritis (which is associated with elevated serum gastrin) might have an increased risk of cancer progression." (PMID 38069171, 2023). "Therefore, in the present study, we examined how gastrin may act on melanoma cells." (PMID 38069171, 2023). "Two representative melanoma cell lines, SK-MEL-2 and G-361, were explored as putative models for the actions of gastrin (see Section 4 for details for the main features of these cells)." (PMID 38069171, 2023). "Initial experiments confirmed the absence of a proliferative effect of gastrin on melanoma cells (See Supplement 1)." (PMID 38069171, 2023). "We do not propose that melanoma patients are more likely than any other group to exhibit increased serum gastrin." (PMID 38069171, 2023). "There is some evidence that melanoma cells express CCK2R, suggesting that gastrin may act on these cells." (PMID 38069171, 2023). "We suggest that gastrin liberates factors from stromal cells (i.e. members of the EGF and IGF families have already been established as gastrin targets in other systems) which then stimulate melanoma invasion and migration." (PMID 38069171, 2023). "In two melanoma cell lines (SK-MEL-2 and G-361), we confirmed that gastrin did not increase cell proliferation." (PMID 38069171, 2023).
ovulation (1 paper, 2023). The release of a mature ovum/oocyte from an ovary. "Compared to the single model, the combined model of clinical (Ovulation dysfunction) and specific genes (GAST, GPX3, THBS2) was more accurate to predict live birth for IVF-ET patients." (PMID 37777726, 2023).
pancreatic ductal adenocarcinoma (1 paper, 2013). An infiltrating adenocarcinoma that arises from the epithelial cells of the pancreas. "The peptide growth factor gastrin and its receptor, the G-protein coupled cholecystokinin receptor type B (CCKBR), play an integral role in the growth and progression of pancreatic ductal adenocarcinoma (PDAC)." (PMID 25346875, 2013).
pancreatitis (1 paper, 2024). Inflammation of the pancreas. "Caerulein is an analogof cholecystokinin and gastrin that stimulates exocrine and proteolyticsecretion in the pancreas, which consequently induces a fibroinflammatoryreaction or pancreatitis." (PMID 39337472, 2024).
pheochromocytoma (1 paper, 2017). "Thirty patients had tumor markers within 30 days of starting treatment and periodically while on treatment (pancreastatin, gastrin, glucagon, neurotensin; metenephrines for pheochromocytoma/paraganlgioma)." (PMID 29262620, 2017).
polyposis (1 paper, 2022). "First, discontinuation can normalize the elevated gastrin levels associated with long-term PPI use, which in turn can counteract parietal cell hyperplasia and polyposis." (PMID 36258093, 2022).
rectal NETs (1 paper, 2025). "Likewise, NETs from other GI sites have their own attributes, e.g., the stomach has three distinct subtypes of NETs, duodenal NETs have a strong association with familial syndromes and/or gastrin/somatostatin secretion, and colonic and rectal NETs tend to be managed quite differently." (PMID 40361413, 2025).
renal dysfunction (1 paper, 2022). "Because patients with renal dysfunction or using PPI tend to have elevated serum gastrin, it is not suitable to use serum gastrin to screen AIG in such patients." (PMID 35410175, 2022).
Renal failure (1 paper, 2011). "Renal failure results in the retention of uremic toxins and gastrin that damage the gastric mucosa and blood vessels of the gastric wall and result in increased acid production." (PMID 23738110, 2011).
scoliosis (1 paper, 2017). A congenital or acquired spinal deformity characterized by lateral curvature of the spine. "Since this is the first study correlating scoliosis and gastrin levels, further studies are required to better clarify this finding." (PMID 28642644, 2017).
stomach NETs (1 paper, 2017). "Gastrin levels are useful for differentiating various types of stomach NETs." (PMID 28194228, 2017).
Stroke (1 paper, 2021). Sudden impairment of blood flow to a part of the brain due to occlusion or rupture of an artery to the brain. "Also, gastrin was reported to protect the brain from ischemia-induced dysfunction in stroke-prone spontaneously hypertensive rats." (PMID 34412590, 2021).
xanthoma (1 paper, 2022). A non-neoplastic disorder characterized by a localized collection of histiocytes containing lipid. "Endoscopic findings (EAC, endoscopic atrophy classification; nodular gastritis; xanthoma; fundic gland polyp; and incompetence of pylorus), sex, age, gastrin, pepsinogen (PG) I and PG II levels were evaluated." (PMID 35328125, 2022).
tumor (175 papers, 1989 to 2026). "In tumor cells, the GAST gene, which encodes hPG80, is directly regulated by the WNT/β-catenin oncogenic pathway, a pathway activated in many cancers." (PMID 40598473, 2025). "Elevated levels of gastrin have been associated with pro-oncogenic characteristics such as tumor growth." (PMID 38672599, 2024). "Mutated menin proteins exhibited loss of function in suppressing tumor cell proliferation and gastrin expression." (PMID 37492626, 2023). "We report that these mutations and variant promote tumor cell growth and gastrin expression by rendering menin protein unstable and prone to increased degradation." (PMID 37492626, 2023). "PTHLH is regulated by gastrin and it is a growth factor regulator while p21 is a tumor suppressor that causes cell cycle arrest." (PMID 34439938, 2021). "Instead, we decided to investigate 2 other gastrin-induced cellular phenomena that are associated with tumor development." (PMID 32004755, 2020). "Gastrin was early recognized to be the cause of the oxyntic mucosal tumours of enterochromaffin-like (ECL) cell origin in the rodents." (PMID 33266504, 2020). "At present, the evidence that a neoplasm-associated growth affect is due to the hypergastrinemia or the exact role of gastrin in the growth or pathogenesis of these tumors in human chronic hypergastrinemia disorders is not compelling and is a source of debate." (PMID 31623145, 2019). "CCKR is a cholecystokinin receptor that has been linked to gastrin, a circulating hormone that maintains the stomach mucosa while also acting as a powerful cell growth factor in biological processes such as proliferation and tumor transformation." (PMID 38361124, 2024). "These elevated gastrin levels may represent a counter-regulatory mechanism against anorexia associated with tumour growth." (PMID 37533569, 2023). "Greater mRNA expression of GAST was significantly linked to a more advanced tumor stage." (PMID 39282247, 2023). "In addition, there are many pathways that alter immune cells, such as when gastrin is stimulated concurrently with PD-1 AB administration, tumors have less fibrosis, inhibitory Treg lymphocytes, and tumor-associated macrophages." (PMID 34439378, 2021). "However, the number of these tumor-associated M2 macrophages correlated negatively with the immunoreactivity for gastrin peptides in tumor epithelial cells." (PMID 24901518, 2014). "However, our approach was limited by the unavailability of tumour markers such as chromogranin A and serum gastrin, which could have provided additional diagnostic and prognostic information." (PMID 41169289, 2025). "As PPIs are well known to cause gastrin elevation, the longer use of PPIs may result in higher gastrin levels, and this may indicate an association between higher gastrin levels and the risk of tumor recurrence." (PMID 36979807, 2023). "However, the current single secreted biomarkers for pancreatic NETs, such as gastrin, insulin and chromogranin A (CgA), have limited usefulness for diagnostic or prognostic purposes, owing to the complexity and diversity of multiple tumour development and varying responses to different therapies." (PMID 35900839, 2022). "Thus, it is unlikely that advanced stage and tumor destruction of the antral G cells could explain the association found in the present study using prediagnostic serum gastrin measurements." (PMID 33091962, 2021). "In parallel, long‐acting somatostatin analogs (e.g., lanreotide, octreotide, pasireotide) reduce gastrin secretion and hormone‐driven tumor activity, thereby lowering acid output." (PMID 41585576, 2026). "CRC organoids were cultured in a customized growth factor‐reduced medium containing FGF10, A83‐01, SB202190, gastrin, and nicotinamide to better maintain original tumor features." (PMID 41503026, 2026).
tumor (continued). "Based on the suspected tumor type, laboratory tests commonly assess hormone levels such as insulin, gastrin, glucagon, vasoactive intestinal peptide (VIP), and somatostatin to identify functioning PANNETs." (PMID 40427145, 2025). "The strong correlations between neuropeptides PTHLH, NMB, APLN, and GAST with these neurotrophic factors suggest a coordinated mechanism through which tumor cells recruit and sustain neuronal infiltration." (PMID 40805163, 2025). "Although less directly linked to gastrin signaling, STAT3 appears central to the shift from hyperplasia to neoplasia." (PMID 41148791, 2025). "Our study has limited outcome data due to the small number of cases, but it identifies the importance of gastrin that was expressed in all but one tumor with an adverse outcome; moreover, all but one of these more aggressive tumors had a plurihormonal profile." (PMID 40553402, 2025). "PanNETs represent a heterogeneous group of tumours, presenting either as hormonally active tumours (producing gastrin, insulin, glucagon, somatostatin, vasoactive intestinal peptide or growth hormone-releasing hormone) or as non-functioning tumours." (PMID 39949334, 2025). "He noted that the total progastrin product better reflects tumor gastrin synthesis than conventional measures of alpha-amidated gastrin." (PMID 38672239, 2024). "Neuroendocrine cells produce functional hormones like serotonin, insulin, glucagon, and gastrin, depending on the specific subtype of the tumor." (PMID 39211694, 2024). "Functional tumours are uncommon and produce hormones and peptides including insulin, gastrin, vasoactive intestinal peptide (VIP), glucagon, somatostatin, and serotonin." (PMID 39246612, 2024). "Initially, intermittent treatment with somatostatin analogues was chosen, leading to a decrease in gastrin levels, as well as size decrease or even disappearance of the tumor." (PMID 36979851, 2023). "A Kaplan Meier survival curve of untreated control mice compared to mice treated with the CCK-BR targeted NP loaded with GAST siRNA (480 nM) shows a significant survival benefit (p = 0.02) even in mice with a large tumor burden." (PMID 36614194, 2023). "A major benefit of our study is the demonstration of a positive correlation between serum levels of gastrin and type I gNEN tumor recurrence." (PMID 36979807, 2023). "The interaction of gastrin at the CCK (Cholecystokinin) receptor has been found to lead to tumour growth as autocrine, paracrine and endocrine growth pathways cause tumour-associated fibrosis and tumour immune cell alterations." (PMID 37686543, 2023). "Neoplastic changes in type I gNENs are always associated with an elevated concentration of serum gastrin, which exerts a trophic effect on ECL cells sequentially undergoing hyperplasia, dysplasia, and neoplasm formation." (PMID 36979807, 2023). "This study shows that high gastrin levels at the time of diagnosis and a tumor with a low Ki-67 index were correlated with a high recurrence rate of type I gNENs." (PMID 36979807, 2023). "The mean tumor mass of the surviving mice was significantly (53%) less than that of the control mice and the GAST siRNA NP-treated mice that died before the experiment was terminated." (PMID 36614194, 2023). "For instance, according to a case report, a primary tumour derived from cardiomyocytes produced a gastrin peptide, where gastrin is mainly expressed in the stomach and regulates acid secretion." (PMID 36101352, 2022). "With the metastasis of neoplasm cells to lymph nodes, the inhibitory action is abolished, and gastrin is highly expressed again in lymph nodes." (PMID 34976177, 2022). "The results indicated that the tumor formation rate in nude mice from gastrin-overexpressed cells (100%) was higher than that of control cells (50%)." (PMID 34976177, 2022). "Gastrin staining showed no positive expression in the tumor and tumor basal mucosa, but a few gastrin-positive cells were seen in the mucosa around the tumor." (PMID 35508985, 2022).